UBE3A (ubiquitin protein ligase E3A)
Diseases named in the same sentence as UBE3A in open-access papers (continued):
Sharing a sentence is not in itself a finding about the gene and the disease.
epilepsy (41 papers, 2010 to 2026). A brain disorder characterized by episodes of abnormally increased neuronal discharge resulting in transient episodes of sensory or motor neurological dysfunction, or psychic dysfunction. "Another neurodevelopment disorder related to epilepsy is Angelman syndrome (AS), caused by mutations in the UBE3A gene." (PMID 35359577, 2022). "This difference may be attributable to the deficiency of GABAA receptor subunit genes in the 15q11–13 region other than UBE3A, which has been associated with epilepsy and developmental delay." (PMID 35573374, 2022). "Treating the epilepsy phenotype in AS mouse models has often been incomplete or ineffective using targeted reinstatement of Ube3a, particular in older animals." (PMID 35592499, 2022). "Seizures were a prevalent phenotype observed in our patient cohort, and this observation was consistent with the high degree of penetrance of epilepsy in UBE3A-dependent disorders." (PMID 34815418, 2021). "Mutations in TCF4, MEF2C, UBE3A, ZEB2 or ATRX cause phenotypically overlapping, syndromic forms of neurodevelopmental disorders with severe intellectual disability, epilepsy and microcephaly." (PMID 32899411, 2020). "Mutations in TCF4, MEF2C, UBE3A, ZEB2 or ATRX cause phenotypically overlapping, syndromic forms of NDDs with severe intellectual disability, epilepsy and microcephaly." (PMID 31988313, 2020). "Given the very effective rescue of UBE3A protein levels upon P1 ASO injection, we investigated whether administration of the ASO in juvenile (P21) mice (129S2 background) would be equally effective in reinstating UBE3A protein levels and rescuing epilepsy." (PMID 34369389, 2021). "However, a systematic examination of critical developmental windows for reactivation of Ube3a in mice revealed that anxiety, repetitive behaviors, and epilepsy were normalized only if reactivation is done from embryonic development." (PMID 32359368, 2020). "We wondered whether this finding might generalize to other seizure induction paradigms, and furthermore, whether UBE3A overexpression would not exacerbate susceptibility to epilepsy following seizure kindling." (PMID 36134658, 2022). "In addition, there were early reports suggesting that loss-of-function UBE3A mutations, paternal UPD of chromosome 15, or imprinting mutations in AS were associated with relatively milder epilepsy while AS patients with a deletion of chromosome 15q11–13 had more severe epilepsy." (PMID 20808828, 2010). "GABAergic deficits have been implicated in the pathogenesis of neocortical hyperexcitability and epilepsy in AS model mice, and GABA transporter-1 has been proposed as a potential UBE3A substrate." (PMID 30364390, 2018). "The link between UBE3A and epilepsy or alteration in the mTOR pathway has not been extensively studied in human in vitro models until recently." (PMID 35359577, 2022). "The pharmacological reactivation of the paternal Ube3a gene in adult mice was not effective in reducing most symptoms of the disorder including epilepsy." (PMID 32359368, 2020).
epilepsy (continued). "Besides UBE3A, class I and II megadeletions cause the absence of the maternally inherited copies of three GABAA receptor subunit genes (GABRB3, GABRA5, and GABRG3), which are genes implicated in neuronal development, synaptic function, and epilepsy." (PMID 37928900, 2023).
Intellectual disability (35 papers, 2013 to 2025). "Individuals possessing these mutations in maternal UBE3A presented with varying levels of intellectual disability, autistic features, motor deficits, skeletal abnormalities, and a partial penetrance for seizures." (PMID 40316779, 2025). "Clinical features of AS, which include developmental delays, intellectual disability, microcephaly, and seizures, are primarily due to the deficient expression or function of the maternally inherited UBE3A allele." (PMID 36598241, 2023). "We identified a novel variant (c.2029G>C) in the UBE3A in a Chinese family with multigenerational intellectual disability and developmental delay." (PMID 35225435, 2022). "We identified a novel variant (c.2029G>C) in the UBE3A in a Chinese family with multigenerational mental retardation and developmental delay." (PMID 35225435, 2022). "Mutations in several genes encoding regulators of mRNA translation (i.e. FMR1) and protein degradation (i.e. UBE3A) have been associated with an increased risk for autism spectrum disorders and intellectual disability (ASD/ID)." (PMID 27365114, 2016). "UBE3A is a maternally expressed gene, so the loss of maternal UBE3A in neurons due to mutation(s) or paternal uniparental disomy of chromosome 15 causes AS, which is characterized by delayed development, intellectual disability, severe speech impairment, ataxia and additional abnormalities." (PMID 37842090, 2023). "The absence of neuronal UBE3A results in severe neurological symptoms, including speech and language impairments, intellectual disability, and seizures." (PMID 38873093, 2024). "Incidentally, while cortical hyperexcitability may indeed relate to intellectual disability in AS, similar levels of intellectual impairment occur without high-amplitude delta activity in duplication 15q11.2-q13.1 syndrome, in which the UBE3A locus is duplicated rather than deleted." (PMID 32551137, 2020).
autism spectrum disorder (34 papers, 2011 to 2025). A spectrum of developmental disorders that includes autism, and Asperger syndrome. "A gain of function and an overdosage of maternal UBE3A is associated with an increased risk of autism spectrum disorders." (PMID 40076922, 2025). "Recently, we have discovered that excessive dosage of UBE3A gene associates with human autistic spectrum disorders (ASD) through ubiquitinating ALDH1As and down-regulating RA homeostasis." (PMID 32545848, 2020). "UBE3A is an important candidate gene of autism spectrum disorder (ASD), which located at the 15q11–13 region and encodes ubiquitin-protein ligase E3A." (PMID 33308194, 2020). "Loss of neuronal UBE3A expression results in AS, while increased dosage of the gene is associated tightly with autism spectrum disorders (ASD)." (PMID 32751183, 2020). "The UBE3A variants are associated with AS, autism spectrum disorder, epileptic encephalopathy and other neurodevelopmental disorder and 253 different variants of the UBE3A gene have been reported (204 variants for AS; 49 variants for others) in HGMD." (PMID 35225435, 2022). "The UBE3A, Ubiquitin Protein Ligase E3A, is one of the major genes implicated in autism spectrum disorder (ASD) and encodes the E6AP protein, a protein that manifests itself in the brain in an imprinted manner." (PMID 38248358, 2023). "It is reported that 1–2% of all autism spectrum disorder (ASD) contain a duplication of the chromosomal region, and the duplications of the region having only UBE3A are associated with developmental delay." (PMID 37541588, 2023). "Dup15q syndrome is an autism spectrum disorder (ASD) caused by duplications and triplications of the 15q11.2–q13.1 chromosomal region that encompasses UBE3A and other genes." (PMID 34676830, 2021). "The functions of UBE3A extend beyond its link to autism spectrum disorder." (PMID 38248358, 2023). "In addition, UBE3A is duplicated in > 1–2% of patients with autism spectrum disorders—a further indication of the significant role it plays in brain development." (PMID 34593829, 2021). "Moreover, excess dosage of the UBE3A gene markedly increases the penetrance of autism spectrum disorders, suggesting that the expression level of UBE3A must be regulated tightly within a physiologically tolerated range during brain development." (PMID 32751183, 2020). "In addition, downregulation of Cbln1 mRNA was observed in mice carrying a triple dose of Ube3a, a model mouse for autism spectrum disorder." (PMID 32078638, 2020). "Why increased UBE3A dosage is more represented in autism spectrum disorders ?" (PMID 26491538, 2014). "Hence, understanding the effects of Ube3a deletion on mitochondrial-related signaling pathways might shed light on the development of autism spectrum disorders beyond AS and dup15q." (PMID 32532103, 2020). "Duplications of 15q11.2-q13.1 (Dup15q syndrome), including the paternally imprinted gene UBE3A and three nonimprinted gamma-aminobutyric acid type-A (GABAA) receptor genes, are highly penetrant for neurodevelopmental disorders such as autism spectrum disorder (ASD)." (PMID 31312421, 2019).
developmental delay (21 papers, 2013 to 2025). "Consequently, UBE3A is expressed only from the maternal allele in normal neurons, and the loss of maternal UBE3A expression causes AS, which is characterized by a cheerful demeanor, developmental delay, impaired speech and seizures." (PMID 32751183, 2020). "Recent studies confirm that duplications in this region, involving genes such as SNRPN, UBE3A, and GABRB3, are associated with neuronal hyperexcitability and synaptic alterations, resulting in autistic phenotypes with seizures and developmental delay." (PMID 40943430, 2025).
Ataxia (17 papers, 2011 to 2026). Ataxia refers to impaired coordination of voluntary muscle movement. "Loss of Ube3a expression also causes mild cerebellar ataxia in both humans and mice." (PMID 21235769, 2011). "Collaborative work from our laboratory also recently established a connection between UBE3A and the mechanosensitive ion channel PIEZO2, leading to the hypothesis that UBE3A might indirectly regulate PIEZO channels, contributing to the both ataxia and hyperphagia in AS." (PMID 37461494, 2023).
prostate carcinoma (15 papers, 2014 to 2022). A carcinoma that arises from epithelial cells of the prostate gland. "Alterations in UBE3A levels are associated with several human diseases, such as cervical cancer, prostate cancer, and breast cancer." (PMID 32455880, 2020). "In a subset of prostate cancers, UBE3A mediates degradation of the tumor suppressor proteins PML and p27Kip1 and thus acts as an oncogene while in non-small cell lung cancer, UBE3A acts as a tumor suppressor." (PMID 33670160, 2021). "Subsequent researches showed that UBE3A also plays a role in multiple cancers, including Burkitt’s lymphoma, prostate cancer, non-small cell lung cancer and breast cancer." (PMID 33670160, 2021). "The tumor suppressor protein p27Kip1 is also a target for UBE3A-induced ubiquitin-dependent degradation in prostate cancer." (PMID 34421347, 2021). "Moreover, UBE3A acts as an oncogenic protein that directly regulates the protein stability of p27 and clusterin in prostate cancer." (PMID 35368029, 2022). "Notably, the expression level of UBE3A in esophageal cancer was higher than that in large B-cell lymphoma, thymoma, pancreatic cancer, and prostate cancer." (PMID 34421347, 2021). "This is surprising, because in prostate carcinoma cells, UBE3A downregulation corresponds with Ar upregulation, again showing that UBE3A may act in a cell-type-dependent manner." (PMID 32455880, 2020). "In its E3 ligase capacity, UBE3A reportedly interacts with the tumor suppressor promyelocytic leukemia protein (PML) in leukemia, Burkitt's lymphoma, and prostate cancer 29-31." (PMID 34421347, 2021). "Other than PTPN4, no statistical significance was found regarding EIF4G3 or UBE3A expression when prostate cancer tissues were compared to normal tissues in the UALCAN database." (PMID 36042375, 2022).
breast carcinoma (14 papers, 2019 to 2025). "Moreover, UBE3A reportedly causes reduced expression of the oncogenic proteins AIB1 (amplified in breast cancer 1) and Enolase1 (ENO1) in breast cancer cells." (PMID 34421347, 2021). "In this study, we demonstrated that FRMD3, which is significantly downregulated in breast cancer, binds with vimentin through its ubiquitin-like domain, leading to the ubiquitination-mediated degradation of vimentin via recruiting ubiquitin ligase UBE3A in breast cancer cells." (PMID 36631457, 2023). "UBE3A interacted with ENO1 to contribute to its ubiquitination and proteasomal degradation in breast cancer cells." (PMID 37385985, 2023). "Ubiquilin2 and myotubularin-1 recognize vimentin for degradation in skeletal muscle cells to avoid proteotoxic aggregate formation.In breast cancer, FERM domain-containing protein 3 (FRMD3) interacts with ubiquitin protein ligase E3A (UBE3A) to induce vimentin proteasomal degradation." (PMID 38383479, 2024). "In conclusion, our results suggest a mechanism by which FRMD3 interacts with vimentin and ubiquitin ligase UBE3A through its ubiquitin-like domain to promote proteasome degradation of vimentin, thereby exerting a unique function of FRMD3 in breast cancer progression." (PMID 36631457, 2023).
Prader-Willi syndrome (14 papers, 2006 to 2025). "For example, mutations, deletions, and duplications of UBE3A E3 ligase gene can lead to three human neurodevelopmental disorders: Prader-Willi syndrome (PWS), Angelman syndrome (AS) and Dup15q syndrome." (PMID 34512273, 2021). "In the future, we will examine Prader Willi syndrome to further disentangling the electrophysiological roles of UBE3A and GABRB3/GABRA5/GABRG3." (PMID 31312421, 2019). "For Prader-Willi syndrome, caused by a deletion of the paternal segment of 15q11-13, ATFs could activate the silenced maternal UBE3A-ATS with the goal of restoring the critical SNORD116 transcripts that are spliced from UBE3A-ATS." (PMID 24946931, 2014). "For example, when the Snrpn promoter was deleted, with or without the Prader-Willi syndrome imprinting center (PWS-IC), the Ube3a-ATS level was found to be reduced, coupling with significant up-regulation of paternal Ube3a." (PMID 24385930, 2013).
Cognitive impairment (13 papers, 2011 to 2026). Abnormal cognition is characterized by deficits in thinking, reasoning, or remembering. "However, the loss of UBE3A exaggerated cognitive impairments in APPswe/PS1δE9 AD mice and accounted for the decreased dendritic spine density and synaptic dysfunction in Tg2576 mice." (PMID 40076922, 2025). "But the function of UBE3A during nervous system development and how UBE3A mutations give rise to cognitive impairment in individuals with AS and ASDs remains unclear." (PMID 37483450, 2023). "Notably, motor and cognitive deficits as well as seizures are common in patients with duplication of 15q11-q13, which harbors a number of imprinted genes and is associated with increased UBE3A levels." (PMID 35592499, 2022). "Thus, both loss and gain of UBE3A function are associated with neurodevelopmental and cognitive defects." (PMID 27232889, 2016). "Thus, both loss and gain of UBE3A functions result in neurodevelopmental and cognitive defects." (PMID 27232889, 2016). "In the Tg2576 and APPswe/PS1 AD mouse models, soluble UBE3A decreased before cognitive impairments were observed." (PMID 40076922, 2025). "A syntenic 6.3-Mb duplication of the mouse region orthologous to the human 15q11-13 region (including Ube3a) resulted instead in social and cognitive impairments." (PMID 38996019, 2024). "Premature termination of Ube3a-ATS by poly(A) cassette insertion activates expression of Ube3a from the paternal chromosome, and ameliorates many disease-related symptoms in the AS mouse model, including motor coordination defects, cognitive deficit, and impaired long-term potentiation." (PMID 24385930, 2013).
microcephaly (13 papers, 2011 to 2025). A congenital or acquired developmental disorder in which the circumference of the head is smaller than normal for the person's age and sex. "Patients with the deletion phenotype tend to have a more severe phenotype, for example severe microcephaly, more severely impaired communication and more severe seizures than patients with other molecular classes of UBE3A deficiency." (PMID 21235769, 2011). "We hypothesize that if a similar mechanism exists in the neuronal cells, the loss of UBE3A function would cause increased cell death and a reduced neural progenitor pool leading to microcephaly." (PMID 21633703, 2011). "However, some patients carrying UBE3A mutations showed milder phenotype, as they do not present ataxic gait, seizures, microcephaly, and normal EEG." (PMID 23256887, 2012). "This suggests that microcephaly may be caused by either a mechanism that affects cell fate determination and cell proliferation (as in the case of ASPM) or an increase in apoptotic signals in neural progenitor cells (as in the cases of STIL and UBE3A)." (PMID 21633703, 2011). "Although the molecular function of UBE3A-ATS in microcephaly contexts is still obscure, disrupting UBE3A-ATS transcription is noted as a potential therapy to increase UBE3A expression in the gene therapy field." (PMID 37408531, 2023). "Similar to mice lacking UBE3A, mICD mutants showed increased body weight and microcephaly compared to WT mice." (PMID 40877933, 2025). "The identification of UBE3A as an ASPM interactor is not unexpected as more than 80% of AS patients have microcephaly." (PMID 21633703, 2011).
Anxiety (12 papers, 2011 to 2025). Intense feelings of nervousness, tension, or panic often arise in response to interpersonal stresses. "As far as emotional problems are concerned, maternal Ube3a-deficient mice are under chronic stress and exhibit anxiety-like behaviors." (PMID 38716113, 2024). "To investigate whether mICD mice show robust AS behavioral features, we made use of a behavioral test battery well established in Ube3a-centric mouse lines that revealed motor impairment, increased anxiety and deficiencies in species-specific innate behaviors." (PMID 40877933, 2025). "Some studies have shown that Ube3a overexpression mice exhibit core ASD features, learning deficits, anxiety-like behavior, and reduced seizure threshold, while others, despite the overexpression of Ube3a, have much more subtle findings." (PMID 39014349, 2024). "For example, Ube3a overexpression in Camk2a-positive neurons resulted in anxiety-like behaviors, learning impairments, and reduced seizure thresholds (but not social deficits or repetitive behaviors)." (PMID 38996019, 2024). "ASD mice models with FMR1, PTEN, UBE3A, and GABRB3 mutations exhibit learning deficits, stereotypic behaviors, and anxiety phenotypes." (PMID 33519379, 2020). "Our data agree with previous findings showing that transgenic mice with decreased GR expression in the brain (50%) or GR coactivator Ube3a knockout mice display anxiety- and depression-like behaviours with a reduced expression of FKBP51 in the cortex." (PMID 27057368, 2016). "Mouse models of GABRB3 and UBE3A deletions exhibit ASD phenotype including developmental delay, hyperactivity, epilepsy, impaired motor function, learning deficits, and anxiety-related behaviors." (PMID 33519379, 2020).